IL1B (interleukin 1 beta)
Diseases named in the same sentence as IL1B in open-access papers (continued):
Sharing a sentence is not in itself a finding about the gene and the disease.
colitis (continued). "Our findings show that Cyn significantly alleviates TNBS-induced colitis symptoms in mice, as evidenced by reduced body weight loss, colon shortening, DAI score, colon histopathology score, and lower levels of inflammatory factors (IL-1β, TNF-α, and IL-6) compared to the model group." (PMID 39902073, 2024). "This difference may be related to the anti-inflammatory effect of oestrogen, study found that oestrogen decreased the production of macrophage migration inhibitory factor, which affected the susceptibility to inflammation in the colon by reducing the TNF-α and IL-1β production in colitis." (PMID 37907907, 2023). "Our results showed that DSS-induced acute colitis led to impaired autophagy flux in IECs, and that administration of oat beta-glucan could promote autophagy flux in IECs, downregulate the expressions of IL-1β, IL-6 and TNF-α and reduce intestinal inflammation." (PMID 37441529, 2023). "In addition, DSS-induced C57BL/6 mice model of colitis presented decreased levels of IL-1β." (PMID 37367886, 2023). "After induction of colitis by DSS, there was weight loss, diarrhea, fecal bleeding, increased mortality, ulcers, loss of colon, and inflammation configured by cellular infiltration, the elevation of pro-inflammatory cytokines (IL-1β, IL-18, TNF-α, and IL-6) and NO." (PMID 36677021, 2023). "Thus, we proposed that DCA administration may intensify TNBS-induced colitis by regulating pro-inflammatory cytokine IL-1β secretion in macrophages." (PMID 37131223, 2023). "However, another study has reported that myeloid-derived miR-223 inhibits the release of IL-1β by preventing the activation of NLRP3 to alleviate experimental colitis, suggesting that miR-223 may have complex functions in UC." (PMID 38169708, 2023). "In addition to being associated with colitis, fatty liver, gout, etc., it is also positively correlated with levels of inflammatory markers (TNF-α, IL-1β, and IL-6)." (PMID 38032532, 2023). "Recently, a number of independent studies suggested that proper intracellular NLRP3, Caspase-1, ASC and IL-1β levels are a prerequisite to maintain intestinal epithelial integrity, limit pathogen colonization and prevent systemic dispersion of commensal bacteria and severe colitis." (PMID 37891577, 2023). "The S. verbenaca-treated group showed a marked downregulation in the mRNA expression of Il-1β, Il-6, Il-12a and Il-23 (p < 0.05 vs. colitic control group), thus confirming the amelioration in the colonic inflammatory status exerted by the extract in this experimental model of colitis." (PMID 38136191, 2023). "Similarly, IL-1β levels increased significantly in mice with experimental CD-like colitis." (PMID 38283356, 2023). "They showed that it could reduce MDA, NO, MPO, hydroxyproline, TNF-α, IL-1β, IL-6, iNOs mRNA, COX-2 mRNA, IFN-γ mRNA, Bcl-2-associated X protein (Bax), Caspase-1, NF-kB and IκBα and increase IL-10, SOD and GSH in an in vivo model of TNBS-induced colitis." (PMID 36677021, 2023). "In addition, exogenous IL-1β offers protection against acute colitis in Gsdmd knockout mice." (PMID 37891577, 2023). "Similarly, long-term colonization with Blastocystis ST3 could promote faster recovery from colitis and decrease the expression of TNFα and IL-1β in dinitrobenzene sulfonic acid (DNBS)-induced colitis mice." (PMID 37185924, 2023). "Given that FCN1+ macrophage infiltration was increased in human PIBD mucosa, and FCN1high macrophages had high expression of IL-1β, we then investigated whether there was an association between FCNB (the murine homologue of human FCN1) and IL-1β in the mouse model of colitis." (PMID 36932401, 2023). "Importantly, the blockade of IL-1β ameliorated experimental colitis in VAD mice." (PMID 37240022, 2023).
colitis (continued). "Compared with the CT group, a colitis model was successfully constructed in the DSS group, as evidenced by higher weight loss, an increased DAI, shorter colon length, more serious colonic tissue damage, and higher levels of pro-inflammatory cytokines (IL-6, IL-1β, TNF-α, and IL-1α)." (PMID 37505716, 2023). "Furthermore, treatment with NK151, NK173, NK175, or their (3:1:1) mix suppressed IS-induced colitis: they suppressed colonic IL-1β and IL-6 expression and the NF-κB+CD11c+ cell number along with the fecal endotoxin level, meanwhile increasing the IL-10 cytokine level in the colon." (PMID 35631220, 2022). "Therefore, these experiments indicated that the deterioration of the intestinal epithelium barrier induced by IL-37 in DSS-induced colitis under conventional housing circumstances involves the downregulation of IL-1β and IFN-γ expression, which is dependent on NF-κB signaling." (PMID 35836813, 2022). "Therefore, we hypothesized that elevated Il17a and Il1r1 transcripts in colonic Th17 cells may position RORγtS182A mice to develop exacerbated tissue inflammation in response to elevated IL-1β signaling during DSS-induced colitis." (PMID 35294872, 2022). "Enhanced inflammasome activity manifested in mice prior to onset of colitis and the disease could be successfully treated by blockade of NLRP3 inflammasomes or IL-1β signaling demonstrating that symptoms of IL-10 deficiency are mediated by inflammasome perturbation." (PMID 36524121, 2022). "This pathway and associated inflammatory markers could be relevant in colitis as NLRP3 inflammasome activity (critical for caspase 1-dependent release of IL-1β and IL-18) in the CNS has been implicated in the exacerbation of neuroinflammation by DSS-induced colitis in aging mice." (PMID 34983592, 2022). "Q-PCR analysis showed that DSS-colitis-induced up-regulated mRNA expression of Cgas, Il10, Ifnb1, Tnf, and Il1b was significantly reduced in STING deficient mice (For Cgas: p < 0.01; For Il10: p < 0.01; For Ifnb1: p < 0.001; For Tnf: p < 0.001; For Il1b: p < 0.001)." (PMID 36467059, 2022). "While CD40/TNFRS5 is one of the TNF-α receptors involved in colitis associated to IL-1β production, no significant variation was found in TNFα, IL-6, and adiponectin expression levels between HL-ARA and HL + ARA groups compared with the mice fed the Std-ARA diet." (PMID 36558497, 2022). "EVs decreased NF-κB levels and mRNA levels of TNFα, IL-1α, IL-1β and IL-2, and increased mRNA levels of TGFβ and IL-10 in LPS-induced inflammation in human intestinal epithelial cells (HT-29) and reduce inflammation symptoms of dextran sulfate sodium-induced colitis in mice." (PMID 35432276, 2022). "Additionally, the level of IL-1β and TNF-α was also increased in colitis-associated cancer." (PMID 36016583, 2022). "Importantly we see evidence of upregulation of TNF-α, IL-1β, and IL-6 in various brain regions of colitis models, which may be sourced from or interact with neurons, microglia, and other cells." (PMID 34983592, 2022). "Careful examination revealed unexpectedly that Npr1−/− mice developed colitis characterized by shortened colon, evident colonic mucosal damage, increased histopathological score, and higher colonic expression of proinflammatory cytokines interleukin-1B (IL1B) and -6 (IL6)." (PMID 35794311, 2022). "In support of the possibility that colitis-associated inflammatory factors contribute to neuroinflammation, we observed increased plasma concentrations of TNFα, MCP-1/CCL2, IL-6, and IFNγ in colitic mice, as well as increased transcription of Tnf, Il1b, and Il6 in their brains." (PMID 34511110, 2021). "To determine whether the dosing time-dependent anti-colitis effects of CR in mice are associated with berberine and REV-ERBα, we measured colonic MDA and MPO activities as well as IL-1β and IL-6 levels in Rev-erbα−/− mice with colitis after 7 days’ CR treatment." (PMID 34393786, 2021).
colitis (continued). "Furthermore, in another study, administration of GLP-1 coated with sterically stabilized phospholipid micelles significantly improved epithelial architecture and reduced expression of pro-inflammatory cytokines such as IL-1β in dextran sodium sulfate (DSS)-induced mice model of colitis." (PMID 34535873, 2021). "Among genes encoding inflammasome components, IL1B and NLRP3 are highly expressed in colon cancer tissues 40,41, and accumulating evidence points to critical roles of the inflammasomes and IL-1β in dextran sulfate sodium (DSS)-induced colitis and azoxymethane (AOM) plus DSS-induced CAC." (PMID 33686176, 2021). "Additionally, the deletion of miR-301a also protects mice against DSS-induced colitis by rescuing BTG anti-proliferation factor 1 (BTG1) expression and is associated with lowering levels of pro-inflammatory markers such as IL-1β, IL-6, IL-8 and tumour necrosis factor (TNF)." (PMID 34943865, 2021). "Similarly, the roles of ASC, Caspase 11, IL-18, and IL-1β in colitis remain debatable." (PMID 34721422, 2021). "Thus, NLRC4 inflammasome-mediated production of IL-1β and IL-18 might be the key factors protecting the host from colonic inflammation and infection." (PMID 33808793, 2021). "Moreover, chemical-induced colitis in the VDR knockout mice was accompanied by high colonic expression of inflammation, including TNF-α, IL-1α, IL-1β and IL-8, leading to weight loss, ulceration and perforation of the bowel, endotoxemia and increased mortality." (PMID 34576700, 2021). "In the DSS-induced colitis mouse model, Firmicutes and Bifidobacterium were reported to be positively correlated with IL-10 (P < 0.05), Enterobacteriaceae was positively correlated with IL-1β (P < 0.05), and Turicibacter was negatively correlated with IL-10 (P < 0.05)." (PMID 33748287, 2021). "However, the increase in Cxcl2 and Il-1β mRNA expression was significantly suppressed in the colons of IL-4Rα-/- colitis mice (Cxcl2; 5.3 ± 1.7 in WT colitis, 0.5 ± 0.3 in IL-4Rα-/- colitis; p < 0.05, Il-1β; 6.6 ± 2.1 in WT colitis, 0.3 ± 0.1 in IL-4Rα-/- colitis; p < 0.01)." (PMID 33192516, 2020). "Another study of experimental colitis in rats treated with APS found that A high dose of APS (200 mg/kg) or dexamethasone could markedly downregulate the expression of IL1β and TNF-α and upregulate the protein expression of nuclear factors of activated T cells 4 mRNA." (PMID 32265719, 2020). "In berberine‐administrated mice with colitis, levels of such pro‐inflammatory cytokines in the colon and sera were significantly decreased, which was accompanied by a reduction in colonic macrophages and percentages of IL‐6+, IL‐1β+ and TNF‐α+ secreting macrophages among splenocytes." (PMID 33135395, 2020). "In DSS-induced mice UC, parthenolide (5, 10 and 15 mg/kg) is capable of inhibiting the secretions of TNF-ɑ and IL-1β in colon tissue via blocking the phosphorylation and degradation of IκBα and suppressing the phosphorylation of NF-κBp65, suggesting beneficial effects in experimental colitis." (PMID 32063999, 2020). "Colitis can cause intestinal epithelial barrier dysfunction and increase its permeability; furthermore, antigens can enter the intestinal lumen, causing the accumulation of lymphocytes and macrophages and resulting in the release of inflammatory factors and cytokines, such as TNF-α, IL-6, and IL-1β." (PMID 31936300, 2020). "Another study performed in mice model of experimental colitis has shown that treatment of colitic mice with EcN_OMVs could reduce intestinal inflammation by inhibiting the expression of IL-1β, TNF-α and IL-17 and enhancing the expression of IL-10 in colonic tissues." (PMID 32854612, 2020). "As is known to all, IL-1β and TNF-α are representative cytokines that aggravates colitis, the down-regulation of these cytokines caused by Sal treatment in DSS-induced colitis mice might help ease disease." (PMID 31849652, 2019).
colitis (continued). "Treatment with UroA/UAS03 significantly protected from DSS-induced colitis as evident from decreased gut permeability, reduced shortening of colons, increased colon weight/length ratio, reduced inflammation (serum IL-6, IL-1β, TNF-α as well as colonic tissue MPO levels)." (PMID 30626868, 2019). "However, rosiglitazone may function through a PPARγ-independent pathway to suppress IL-6, TNF-α, and IL-1β production, as rosiglitazone administration attenuates colitis in IEC-specific PPARγ KO mice." (PMID 30804707, 2019). "In addition, it has been reported that blockage of IL-1β or IL-18 reduces colitis." (PMID 30823406, 2019). "In addition, the administration of apelin to Il10−/− mice with established colitis resulted not only in an amelioration of disease by lowering the production of pro-inflammatory cytokines such as TNFα, IL-6, and IL-1β but furthermore enhanced intestinal lymphatic function." (PMID 30369924, 2018). "In contrast, during the acute phase of DSS-induced colitis model the innate immune cells, especially neutrophils and macrophages, massively infiltrate the LP, and elevated levels of the pro-inflammatory cytokines they secrete, such as TNFα, IL-1β, and IL-17 are observed." (PMID 30619283, 2018). "The decrease in CMMC activity caused by colitis does not involve a direct effect of IL-1β." (PMID 29933379, 2018). "However, little is understood regarding the impact of colitis and IL-1β on CMMC activity." (PMID 29933379, 2018). "Interestingly, after SPX, the treatment with α7 agonist lost completely its protective effects against colitis, being unable to lower IL-1β concentrations and exacerbating TNBS-induced increase of IL-6 levels, while leaving unmodified IFNγ and IL-10 colonic content with respect to SPX/C mice." (PMID 29167641, 2017). "Furthermore, IL-1β activity in colitis is correlated with the severity of the disease." (PMID 28854223, 2017). "In addition, DS reduced interleukin-1β (IL-1β) secretion and decreased neutrophil infiltration and monocyte activation, which both contributed to a reduction of the antigenic load in hapten-induced colitis in the rat." (PMID 28450899, 2017). "In conclusion, these results suggest that the NLRP3 inflammasome may have a protective effect on Th2 cytokines- and immune system-mediated experimental colitis; both the inflammasome derived IL-1β and IL-18 contribute to this protection via different mechanisms." (PMID 27966619, 2016). "Furthermore, HBO2 treatment alone did not change the expression of proinflammatory cytokines in the colon, MLN, or spleen of the control mice; however, DSS-induced colitis resulted in a significant IL-1β and IL-6 gene upregulation in the colonic tissue and IL-2 gene upregulation in the MLN." (PMID 27656047, 2016). "Plasma levels of IL-1β, IL-6, IL-10, IL-17, TNFα, and IFNγ were detected in blood samples from all experimental mice group at two different time points, one corresponding to the acute phase of colitis (day 25), and one at the end of the recovery phase (day 37)." (PMID 26973525, 2016). "Dietary astaxanthin suppressed colitis and colitis-related colon carcinogenesis, partly through inhibition of NF-κB, and downregulation of the messenger ribonucleic acid (mRNA) expression of inflammatory cytokines, including interleukin-1β (IL-1β), interleukin-6 (IL)-6, and cyclooxygenase (COX)-2." (PMID 24473167, 2014). "This could be attributed to a number of factors relating to the use of IBS-20 in vivo including the inability to inhibit the TNBS-induced epithelial barrier breakdown or to block production of IL-1β, a major pro-inflammatory cytokine implicated in TNBS-induced colonic inflammation." (PMID 22461841, 2012). "In DSS-induced colitis mice, oral Casein-PE@TNF-Ab markedly increased colon length and suppressed colonic TNF-α, IL-1β, and MPO levels by 82%, 61%, and 62%, respectively, versus DSS." (PMID 41985594, 2026).
colitis (continued). "Serum analysis showed that EGT significantly lowered DSS-elevated levels of IL-6, IL-1β and TNF-α, confirming its systemic anti-inflammatory effects in this colitis model." (PMID 41530565, 2026). "The results showed that the concentrations of inflammatory factors in the colon tissue of colitis mice after oral gavage of A. actinomycetemcomitans were significantly higher than those in the DSS group (Il-6, P = 0.031; Il-1β, P = 0.005; Tnf-α, P < 0.0001)." (PMID 41531455, 2026). "Blocking the NAD+ salvage pathway inhibited the secretion of IL‐1β, IL‐6, IL‐8, IL‐18, and TNF‐α in the serum and reduced the expression of TNF‐α in the tissues of F. nucleatum‐infected IFX‐treated DSS‐induced colitis mice." (PMID 39739648, 2025). "In models of dextran sulfate sodium (DSS)-induced colitis, Akkermansia muciniphila (AKK) demonstrated protective effects by decreasing inflammatory cytokines (TNF-α, IL-1β, IL-6) and inhibiting NLRP3 inflammasome activation." (PMID 40299512, 2025). "Arbutin has been reported to significantly down-regulate the levels of inflammatory cytokines (IL-1β, IL-6, and TNF-α), iNOS, and cyclooxygenase-2 (COX-2) in colitis mice." (PMID 40078988, 2025). "Growing evidence indicates that during the onset of colitis, the body produces large amounts of pro-inflammatory cytokines (IL-6, TNF-α, IL-1β, etc.), primarily derived from macrophages and neutrophils." (PMID 41008172, 2025). "Preclinical studies have demonstrated that VX-765 administration effectively reduces IL-1β secretion and attenuates inflammation in models of inflammatory diseases and alleviates DSS-induced colitis in mice by suppressing caspase-1 mediated pyroptosis." (PMID 40869366, 2025). "G. lemaneiformis suppressed TNF-α, IL-1β and IL-6 levels in dextran sulphate sodium (DSS)-induced colitis in Balb/c mice and IEC-6 cells, improving intestinal barrier function and microbiota structure, thus preventing intestinal inflammation." (PMID 40077614, 2025). "After the onset of colitis, IL-10−/− mice have a higher secretion of inflammatory cytokines than wild-type mice, including TNF-α, IL-1β, IL-6, and IFN-γ." (PMID 40732952, 2025). "The study in this work demonstrated that supplementation with CW prevents the excessive formation of TNF‐α, IL‐1β, and IL‐6 in the serum of mice with DSS‐induced colitis." (PMID 39830908, 2025). "In a mouse model of dextran sulfate sodium (DSS)-induced colitis, genistein significantly suppressed NLRP3 inflammasome activation via the TGR5–cAMP signaling axis, leading to reduced IL-1β secretion and improved clinical outcomes." (PMID 41433336, 2025). "Pro-inflammatory cytokines (IL-1β, IL-6, TNF-α) were markedly elevated in the Colitis group, while anti-inflammatory IL-10 was suppressed (p < 0.01)." (PMID 40574090, 2025). "In dextran sodium sulfate (DSS)-induced colitis in C57BL/6 mice, verbascoside alleviated disease symptoms, modulated cytokine expression (upregulated IL-10, downregulated IL-1β and TNF-α), and inhibited JAK2/STAT3 and NF-κB pathways." (PMID 40724000, 2025). "Muscadine wine polyphenols were shown to prevent weight loss and colon shortening, downregulate the NF-κB pathway and secretion of IL-1β, IL-6, and TNF-α in the colon of mice with DSS-induced colitis." (PMID 40732952, 2025). "The study also is the first time to show that the level of IL‐1β, TNF‐α, and IL‐6 in the serum of colitis mice was greatly decreased by IF." (PMID 39898122, 2025). "DSS-induced colitis is characterized by elevated MPO activity, pro-inflammatory cytokines (TNF-α, IL-6, IL-1β), and lipid peroxidation, alongside depleted antioxidant defenses (SOD, CAT, GSH)." (PMID 41395463, 2025). "The APS-H-treated colitis mice had down-regulated blood levels of IL-6, TNF-α, and IL-1β, whereas the DSS-treated mice had increased serum levels of these cytokines." (PMID 41010526, 2025).